CYP24A1 (cytochrome P450 family 24 subfamily A member 1)
Diseases named in the same sentence as CYP24A1 in open-access papers (continued):
Sharing a sentence is not in itself a finding about the gene and the disease.
Follicular Cyst (1 paper, 2021). Cyst due to the occlusion of the duct of a follicle or small gland. "In the ovary, CYP27B1 and CYP24A1 were found exclusively in the granulosa cells of healthy follicles with a lack of positive staining in follicular cysts." (PMID 33095902, 2021).
glioblastoma (1 paper, 2018). The most malignant astrocytic tumor (WHO grade IV). "Next, we determined if 1,25D exerted actions on the expression of SERT, MAO-A, MAO-B, and CYP24A1 in the human glioblastoma cell line, U-87 MG (U87), which does not exhibit serotonergic neuronal characteristics." (PMID 30008960, 2018).
glottic carcinoma (1 paper, 2025). "Associations between VDR/CYP24A1 polymorphisms and the recurrence risk of glottic carcinoma further emphasize the need for genotype-guided therapy." (PMID 41246358, 2025).
head and neck cancer (1 paper, 2023). A primary or metastatic malignant neoplasm affecting the head and neck. "Another study examined the influence of genetic sequence variants (GSVs) in the vitamin D3 metabolism pathway, candidate-based GSVs, i.e., VDR, GC, CYP24A1, CYP27A1, CYP27B1, and CYP2R1, on overall survival (OS) and second primary cancer (SPC) in head and neck cancer patients." (PMID 37299554, 2023).
hyperlipidemia (1 paper, 2021). "Cyp24a1 participates in vitamin D hydroxylation and fatty acid omega oxidation and it is associated with hyperlipidemia in rats." (PMID 34208498, 2021).
hypocalciuric hypercalcemia (1 paper, 2024). "Moreover, we identified a heterozygous variant in the CYP24A1 gene in one patient (CA0029) with hypocalciuric hypercalcemia." (PMID 38586466, 2024).
Insulin resistance (1 paper, 2025). Increased resistance towards insulin, that is, diminished effectiveness of insulin in reducing blood glucose levels. "Furthermore, CYP24A1, which plays a crucial role in the regulation of active vitamin D, demonstrated increased expression in the context of insulin resistance." (PMID 39906623, 2025).
interstitial nephritis (1 paper, 2020). Inflammation of the renal tubules and supporting tissues of the kidney. "CYP24A1 and CYP27B1 expression in the tubules is elevated in CKD patients with acute renal inflammation, ie, renal vasculitis or interstitial nephritis, and in adenine‐treated uremic rats with marked interstitial fibrosis, severe tubular dilatation, microcystic change, and foci of tubular atrophy." (PMID 32617522, 2020).
invasive carcinoma (1 paper, 2010). A carcinoma that is not confined to the epithelium, and has spread to the surrounding stroma. "In contrast, CYP24A1 expression was augmented in carcinomas (56.0% in in situ and 53.7% in invasive carcinomas) when compared with that in benign lesions (19.0%)." (PMID 20831823, 2010).
large cell lung carcinoma (1 paper, 2019). "We found the expressions of CYP2D6 were significantly up‐regulated in large cell lung carcinoma, AC and SCC patients compared with the normal samples (P < 0.05), and CYP24A1 and CYP20A1 were found overexpressed in the AC (P < 0.05)." (PMID 31264381, 2019).
laryngeal carcinoma (1 paper, 2024). Carcinoma that arises from the laryngeal epithelium. "Through the expression of CYP24A1 and CYP27B1, laryngeal cancer cells can produce vitamin D3 metabolites 1,25(OH)2D3 and 24,25(OH)2D3 at biologically relevant levels." (PMID 38730587, 2024).
liver disease (1 paper, 2022). "Furthermore, the genetic variants of CYP24A1 (rs6013897) are associated with inflammatory reactions, which should be clarified in liver diseases." (PMID 35919232, 2022). "CYP24A1 induces low serum levels of 25(OH)D3, which has been shown with liver disease severity in studies with non-alcoholic fatty liver disease (NAFLD) and patients with hepatitis C (HCV)." (PMID 35919232, 2022).
malignant glioma (1 paper, 2019). A grade III or grade IV glioma arising from the central nervous system. "All of these results demonstrated that CYP24A1 was highly expressed in malignant glioma tissues and acidic microenvironment, where the CSCs were existed." (PMID 30631035, 2019). "Our study suggested that it might be a potential treatment strategy to target CYP24A1 for inhibiting the growth of malignant glioma under acidic microenvironment." (PMID 30631035, 2019). "Our study indicates that the acidosis–CYP24A1–vitamin D pathway may be a key regulator of the cancer stem cell phenotype in malignant glioma and point out the potential value for the utilization of vitamin D to target cancer stem cells and to restrain the growth of malignant glioma in the future." (PMID 30631035, 2019).
mammary adenocarcinoma (1 paper, 2014). "When MCF7 human mammary adenocarcinoma cells are exposed to an inflammatory microenvironment cyp24a1 mRNA shifts from monosomal to polysomal fractions." (PMID 24416388, 2014).
mastitis (1 paper, 2022). Inflammation of breast tissue during lactation or postpartum due to an obstructed duct or infection. "Additionally, a Streptococcus uberis (S. uberis) bovine mastitis model observed localized expression increased for CYP27B1 in milk CD14+ cells during active mastitis, while CD14- cells saw increased CYP24A1." (PMID 36144467, 2022).
melanocytic naevi (1 paper, 2015). "The findings suggest that elevated CYP24A1 expression may be important for the formation of melanocytic naevi and early melanomagenesis." (PMID 25970336, 2015).
metabolic diseases (1 paper, 2021). "Although no studies have shown a relationship between the polymorphisms of CYP24A1, CYP27B1, and NAFLD, these variants have been extensively investigated in other diseases, such as organ-specific autoimmune endocrine diseases, CVD, metabolic diseases, and multiple cancers." (PMID 34484304, 2021).
metastasis (1 paper, 2022). The spread or migration of cancer cells from one part of the body (where they first appeared) to another. "For example, CLDN2 expression was recently linked to increased incidence of CRC-associated liver metastasis, whereas CXCR4 and CYP24A1 are increasingly recognized as prognostic markers for CRC progression." (PMID 35159043, 2022).
metastatic cancers (1 paper, 2022). A carcinoma which has spread from the original site of growth to another anatomic site. "Similar to the VDR expression, CYP24A1 expression was significantly decreased in patients with multiple metastatic cancers." (PMID 36362766, 2022).
nodular goiter (1 paper, 2011). Goiter characterized by discrete tissue mass(es) that may or may not produce thyroid hormones. "Among of them, there was a significantly distinct methylation profiling of ABCB4, CYP1B1 and CYP24A1 and SLC1A2 between nodular goiter and normal thyroid tissues (P < 0.05)." (PMID 21988780, 2011).
oral lichen planus (1 paper, 2020). Oral lichen planus is a chronic inflammatory oral condition of unknown aetiology characterized by T-cell-mediated chronic immune response and abnormal epithelial keratinization cycle. "Correlation of MTHFR gene, CYP27b1, and cyp24a1, with the risk of developing oral lichen planus." (PMID 33527053, 2020).
osteoarthritis (1 paper, 2016). A noninflammatory degenerative joint disease occurring chiefly in older persons, characterized by degeneration of the articular cartilage, hypertrophy of bone at the margins and changes in the synovial membrane. "Future studies must also examine osteoarthritis in the Cyp24a1-/- mouse, which lacks 24,25(OH)2D3, to definitively demonstrate the role of 24,25(OH)2D3 in osteoarthritis progression." (PMID 27575371, 2016).
ovarian tumors (1 paper, 2021). "Studies showed that CYP24A1 could act as an oncogene and was upregulated in a variety of tumors, such as human breast, lung, colon, and ovarian tumors." (PMID 35087744, 2021).
pancreatic disorder (1 paper, 2023). "Future research on CYP24A1 expression in canine pancreatic tumor might be beneficial to understand the role of vitamin D metabolism in the pathogenesis of canine pancreatic tumors, a pancreatic disorder that is uncommon but crucial in dogs." (PMID 37808100, 2023).
peritonitis (1 paper, 2014). Inflammation of the peritoneum (tissue that lines the abdominal wall and covers most of the organs in the abdomen). "This is endorsed by the increased expression of CYP27B1 and decreased expression of CYP24A1 in PD cells from peritonitis patients." (PMID 25549329, 2014).
psychosis (1 paper, 2018). "Our findings could suggest that factors other than current vitamin D levels influence total ventricular volume in patients with psychosis, as we found this measure to be associated with CYP24A1 polymorphisms (rs6013897)." (PMID 30142216, 2018).
pulmonary fibrosis (1 paper, 2022). Chronic progressive interstitial lung disorder characterized by the replacement of the lung tissue by connective tissue, leading to progressive dyspnea, respiratory failure, or right heart failure. "We tested the level of fatty acid metabolism and the predictive value of Abca3 and Cyp24a1 in rat models with different degrees of pulmonary fibrosis to verify the accuracy of the prediction results." (PMID 36211517, 2022).
relapsing-remitting MS (1 paper, 2017). "In this case-control study, the expression of genes encodingvitamin D receptor (VDR) and CYP24A1 in relapsing-remitting MS (RR-MS) patientswas compared with normal individuals in the Iranian population." (PMID 28836398, 2017).
renal cell carcinoma (1 paper, 2021). "There is increasing evidence that vitamin D metabolites influence carcinogenesis, and, indeed, CYP24A1 has been found to be up-regulated in tissues of patients with renal cell carcinoma and has been proposed as a candidate oncogene for colorectal tumorigenesis." (PMID 33652839, 2021).
renal fibrosis (1 paper, 2020). A final common manifestation of a wide variety of chronic kidney diseases characterized by glomerulosclerosis and tubulointerstitial fibrosis. "ESA treatment also reduced renal fibrosis markers, as well as increased Cyp27b1 and reduced Cyp24a1 mRNA expression." (PMID 32476270, 2020).
schizophrenia (1 paper, 2022). A major psychotic disorder characterized by abnormalities in the perception or expression of reality. "We have also described over-expression of VDR, CYP27B1, and CYP24A1 in peripheral blood of patients with schizophrenia compared with healthy subjects in our previous study." (PMID 35279108, 2022).
seminoma (1 paper, 2023). A radiosensitive malignant germ cell tumor found in the testis (especially undescended), and extragonadal sites (anterior mediastinum and pineal gland). "CYP24A1, i.e., one of the Vitamin D regulatory genes, which can help to distinguish between pure seminomas and NSGCT, can serve as a prognostic tool to predict good sperm quality and, thus, fertility." (PMID 37242266, 2023). "Using TCGA mRNA expression of anabolic (CYP2R1, CYP27A1 and CYP27B1) and catabolic (CYP24A1) Vitamin D enzymes, positive (PTHLH, IFNG, and TNF) and negative (FGF23) feedback regulators could also clearly distinguish between pure seminomas and NSGCT." (PMID 37242266, 2023).
skin cancer (1 paper, 2017). "Our analysis also identified several new UV target genes, including CYP24A1, GJA5, SLAMF7 and ETV1, which were frequently dysregulated in human squamous cell carcinomas, highlighting their potential as new molecular targets for prevention or treatment of UVR-induced skin cancers." (PMID 28211524, 2017).
thyroid tumor (1 paper, 2021). A benign or malignant neoplasm affecting the thyroid gland. "Interestingly, it has been reported that mice with CYP24A1 knockout exhibited a fourfold reduction in thyroid tumor growth compared with wild-type CYP24A1 mice." (PMID 34422647, 2021).
uveal melanoma (1 paper, 2019). A melanoma derived from melanocytes of the uveal tract. "The correlation was statistically significant only for CYP24A1 expression in comparison to the melanin levels in uveal melanoma (p = 0.020)." (PMID 31235702, 2019). "This is significant because until now there has been no paper published, that would describe presence of VDR, hydroxylases CYP27B1 and CYP24A1, and RORα and RORγ in the human uveal tract and uveal melanomas." (PMID 31235702, 2019). "The Wilcoxon signed-rank test showed that the immunostaining CYP24A1 distribution in uveal melanoma and uveal melanocytes, uveal melanoma and other uveal cells significantly differ from each other (p < 0.001)." (PMID 31235702, 2019). "In conclusion, we provide an evidence for the presence of the VDR, CYB27B1, CYP24A1, RORα and RORγ in uveal cells, which changes in uveal melanomas and suggest that these proteins are involved in clinical presentation and represent targets for novel therapeutic approaches." (PMID 31235702, 2019). "The levels of VDR, CYP24A1, CYP27B1 and RORs were always the lowest in the cells of uveal melanoma and higher in normal uveal melanocytes and other normal uveal cells." (PMID 31235702, 2019).
ZIKV infection (1 paper, 2024). "The observed downregulation of CYP24A1 during ZIKV infection may further indicate specific viral interference with VDR gene expression." (PMID 38839691, 2024). "However, the inhibitory effect of ZIKV infection on CYP24A1 expression was less pronounced in the presence of VitD3 at both 12 hpi (p = 0.0005 and 0.0058, respectively) and 48 hpi (p = 0.001 and 0.0023, respectively)." (PMID 38839691, 2024). "The effect of ZIKV infection on the VitD3 system of monocytes was investigated by determining the relative levels of expression of VDR, CYP24A1, and CAMP mRNA by RT-qPCR." (PMID 38839691, 2024). "The results showed a significant decrease in the expression of vitamin D3 receptor (VDR), cytochrome P450 family 24 subfamily A member 1 (CYP24A1), and cathelicidin antimicrobial peptide (CAMP) genes upon ZIKV infection." (PMID 38839691, 2024). "The results show that ZIKV infection suppresses the expression of VDR, CYP24A1, and CAMP in monocytes, suggesting an alteration of the VitD3 signaling pathway." (PMID 38839691, 2024). "The levels of CYP24A1 and CAMP mRNA were significantly lower at 12 and 48 hpi, two critical time points of ZIKV infection, in ZIKV-Mon and ZIKV-VitD3-Mon when compared to VitD3-Mon." (PMID 38839691, 2024).
tumor (127 papers, 2010 to 2025). "Pathway analysis linked circ-CYP24A1 to immune and cell cycle regulatory pathways, highlighting its role in tumor-stromal communication." (PMID 40303340, 2025). "Apart from its diagnostic value, circ-CYP24A1 showed a marginally positive correlation with tumor thickness (Pearson r = 0.8689, p = 0.0558)." (PMID 36291882, 2022). "Seven single nucleotide polymorphisms (SNPs) were genotyped, the expression of CYP27B1 and CYP24A1 were measured in 153 tumor samples and their associations with genotypes and patient survival were also analyzed." (PMID 25544771, 2015). "When the clinical data were taken into consideration, we observed that CYP24A1 expression was associated with tumor location (proximal to distal colon) (rs=0.48; p<0.02)." (PMID 26260259, 2015). "Yet, cyp24a1 is not only associated with a poor response to vitamin D3-based therapeutics, it rather appears to be overexpressed in various tumor types." (PMID 24416388, 2014). "In addition, our aim was to investigate possible associations of VDR and CYP24A1 expression and tumour characteristics, as well as patient outcomes." (PMID 36362766, 2022). "It is possible that alterations to the tumor microenvironment may lead to increased CYP24A1 activity in malignant tissue, creating a local deficiency in vitamin D levels and negating its anti-proliferative effects." (PMID 34298730, 2021). "It was confirmed that the abnormal expression of CYP24A1 was related to cancer risk and might contribute to tumor aggressiveness." (PMID 34035992, 2021). "Enhancement of 25-(OH)D-1α-OHase activity will add to availability of 1,25-(OH)2D3 in the gut epithelium and consequently lessen the tumorigenic potential of COX-2, while simultaneous down-regulation of CYP24A1 could reduce the risk of further tumor progression." (PMID 24213465, 2012). "The promoter methylation level, quantified based on these three significant CpG sites, was lower in tumor tissues compared to normal tissues, suggesting promoter hypomethylation of CYP24A1." (PMID 39858498, 2025). "CYP24A1 was significantly overexpressed in tumor tissues compared to normal tissues in both the dataset with 692 unpaired samples and the dataset with 100 paired samples from the TCGA database (p < 0.05)." (PMID 39858498, 2025). "circ-CYP24A1 was significantly overexpressed in plasma-derived exosomes from cSCC patients and correlated with tumor size, thickness, and serum SCC-Ag levels." (PMID 40303340, 2025). "In pre-clinical cancer therapy research, CYP24A1 inhibitors are able to reduce the breakdown of 1,25 (OH)2D and enhance its anti-tumor effect, and show potential therapeutic value." (PMID 40630116, 2025). "The CYP24A1 is silenced in some cancer cells, such as tumor-derived endothelial cells of the colon, resulting in tumor-suppressive effects with vitamin D treatment." (PMID 40362248, 2025). "Both analogues also significantly decrease cell proliferation in tumour cells, although only compound 4 increases the mRNA expression of CYP24A1, a target gene of 1,25D3." (PMID 40572600, 2025). "In line with our results, a previous study from Austria reported that the methylation level of two regions within the promoter of CYP24A1 was lower in tumor tissues than in adjacent normal mucosa, although this difference was not statistically significant." (PMID 39858498, 2025). "Mechanistic summary: In CRC, CYP24A1 overexpression—driven by genetic, epigenetic, and inflammatory mechanisms—accelerates 1,25(OH)2D3 degradation, impairing vitamin D-mediated tumor-suppressive functions and contributing to therapeutic resistance." (PMID 41228419, 2025). "Inflammatory cytokines and microbial metabolites in the tumor microenvironment further upregulate CYP24A1, creating a feedback loop that blunts vitamin D signaling." (PMID 41228419, 2025). "The inhibition of exosomal circ-CYP24A1 was shown to possibly also affect SCC progression by suppressing the tumor’s locally invasive and metastatic dynamic." (PMID 38473864, 2024).